CCNE1 (cyclin E1)
Diseases named in the same sentence as CCNE1 in open-access papers (continued):
Sharing a sentence is not in itself a finding about the gene and the disease.
breast carcinoma (continued). "Interestingly, among the over-expressed genes, MT2A (metallothionein 2A) and CCNE1 (cyclin E1) are associated not only with breast cancer, but also with cadmium induction suggesting that the microarray analysis is identifying genes relevant to both cadmium exposure and breast cancer." (PMID 24376830, 2013). "Induction of cyclin E1 was also identified in our previous acute cadmium study on breast cancer cells." (PMID 24376830, 2013). "It has been reported that the expression levels of cyclin D1 and cyclin E1 are related to the malignant degree of cancers, including glioma, breast cancer, bladder cancer, etc.." (PMID 23383003, 2013). "Consistent with a previous observation that cyclin E1 is elevated in basal-like breast cancer, we found that cyclin E1 was also elevated in basal-A tumors compared to all other types." (PMID 24265703, 2013). "Although CCNE1 amplification was restricted to a subset of cancers harbouring 19q12 amplification, we set out to investigate if breast cancer cells harbouring CCNE1 amplification would be selectively dependent on the expression of this gene for their survival." (PMID 22433433, 2012). "Although our results support the contention that CCNE1 is one of the drivers of this amplicon, in this study CCNE1 was amplified only in 5 out of 16 breast cancers harbouring 19q12 amplification." (PMID 22433433, 2012). "Although CCNE1 has been proposed as a driver of this amplicon in breast cancer, CCNE1 was amplified in only 5 out of the 16 primary breast cancers harbouring amplification of the 19q12 locus." (PMID 22433433, 2012). "It should be noted, however, that CCNE1 was shown to be amplified only in a subset of breast cancers harbouring 19q12 amplification." (PMID 22433433, 2012). "As miR-137 interferes with the ERRα-CCNE1 axis, its role and therapeutic value in breast cancer, especially in the HER2 positive breast cancer are worth further investigation." (PMID 22723937, 2012). "Both CCNE1 and CCNE2 are expressed at higher levels in breast cancer, with an association of both genes to increased tumour grade, estrogen receptor (ER) negative status, progesterone receptor negative status, and proliferative index by Ki67 staining." (PMID 20180967, 2010). "This is consistent with studies in estrogen-responsive breast cancer cell lines where cyclin E2 is a highly estrogen responsive target, whereas cyclin E1 is only marginally increased." (PMID 20180967, 2010). "Notably, AKT1, ERBB2 (HER2), CDK4, and CCNE1 are significantly amplified in tumor samples while PIK3CA displays the lower expression level in breast cancer." (PMID 40725120, 2025). "They intricately control cell cycle advancement by acting on essential proteins like cyclin E1, cyclins, and cyclin-dependent kinase increases, causing cell cycle halt at critical checkpoints including G1/M and G2/M transitions in MCF-7 human breast cancer cells." (PMID 40612872, 2025). "Interestingly, cytoplasmic Cyclin E1 was reported to predict breast cancer recurrence and response to neoadjuvant chemotherapy." (PMID 38167507, 2024). "Moreover, the cyclin E1 locus is frequently amplified in human malignancies, especially in ovarian cancer and breast cancer but also in glioma." (PMID 38184514, 2024). "Moreover, miR-497 (logFC=1.451) in breast cancer cells regulates the growth of cancer cells by targeting CCNE1." (PMID 39202109, 2024). "However, CCNE1 amplification has little relationship with human epidermal growth factor receptor 2 (HER2)-positive breast cancer prognosis and anti-HER2 targeted therapy efficacy." (PMID 36393842, 2022). "Moreover, in silico meta-analysis of JUNB protein levels showed its association with poor survival in breast cancer patients and identified a positive correlation between JUNB, CCNE1, and TGFB2 expression levels in these tumors." (PMID 36494864, 2022).
breast carcinoma (continued). "Clinical samples and breast cancer cell lines also confirmed the expression of CCNE1." (PMID 33791304, 2021). "Therefore, LINC02568 plays a pro-oncogenic role in breast cancer progression by targeting the miR-874-3p/CCNE1 axis." (PMID 37303942, 2021). "Furthermore, our mechanistic investigations suggested that miR-874-3p-mediated suppressive effects in breast cancer cells were mediated by targeting CCNE1." (PMID 37303942, 2021). "Consequently, we examined the relationship between BRCA1 methylation and cyclin E1 protein expression by interrogating the breast cancer dataset of the TCGA." (PMID 34465787, 2021). "Additionally, we identified a significant association of genes involved in treatment response in breast cancer with genes producing splicing-derived neoepitopes (ERBB2, ESR1, TIMP1, ABCC3) or potentially depleted self-epitopes (AKT1, CCNE1, RET, TFF3)." (PMID 34529669, 2021). "Analyzing TCGA BRCA clinical data, we further found that CCNE1 expression in breast cancer could be related to TNM stage and ER/PR status." (PMID 33791304, 2021). "On the other hand, HuR increases the level of cyclin-E1 in breast cancer cells." (PMID 34604242, 2021). "Overall, these data implicate increased cyclin E1 protein stability, rather than gene amplification, as the cause for high cyclin E1 levels observed in BRCA1 mutated breast cancer." (PMID 34465787, 2021). "Furthermore, miR-874-3p mediated suppressive effects in breast cancer cells by targeting cyclin E1 (CCNE1)." (PMID 37303942, 2021). "Moreover, the TCGA BRCA data showed CCNE1 was overexpressed in TNBC than luminal-type breast cancer and normal samples, while high CCNE1 expression in TNBC meant bad survival." (PMID 33791304, 2021). "Finally, the increase in expression of the genes CCNE1, FANCI, RFC4, CDC6, and YWHAZ associated with poor prognosis in luminal A breast cancer (OS, HR:2.54, CI 1.69–3.82, log rank p = 3.6 × 10−6; RFS, HR:1.84, CI 1.53–2.22, log rank p = 6.5 × 10−11)." (PMID 33925616, 2021). "CCNE1 was overexpressed in several types of cancer, including breast cancer." (PMID 33791304, 2021). "We assessed the cyclin E1 degradation machinery by IHC in our familial breast cancer cohort." (PMID 34465787, 2021). "Copy number (CN) alterations in ctDNA were also associated with breast cancer subtype, with CN alterations in MYC, PIK3CA, EGFR, CCNE1, CDK6, BRAF and MET more common in TNBC (q = 0.01, q < 0.0001, q = 0.001, q < 0.0001, q = 0.0003, q = 0.0002 and q = 0.01, respectively)." (PMID 33893289, 2021). "Through gain and loss of function and rescue experiments, we confirm that MIR200CHG regulates the expression of tumor-associated proteins CDKN2A, cyclin D1, cyclin E1, BCL2, BAX, MMP1, MMP2, and MRP1 by binding YB-1, thereby promoting breast cancer proliferation, invasion, and resistance." (PMID 34272387, 2021). "In addition, by binding to the 3′UTR of cyclin E1, which is overexpressed in breast cancer, HuR improves cyclin E1 mRNA stability and thus increases its protein expression." (PMID 32653017, 2020). "There were negative expression correlations of hsa-let-7a-5p-CCNB2, hsa-let-7c-5p-CCNB2, hsa-let-7a-5p-AURKB, hsa-miR-30a-5p-CDC20, hsa-miR-30a-5p-MYBL2, hsa-miR-29c-3p-OIP5, hsa-miR-10b-5p-CHAF1B, hsa-miR-195-5p-CCNE1, and hsa-miR-497-5p-CCNE1 in ERα positive breast cancer." (PMID 32500028, 2020). "In addition, we discovered six genes: CCNE1, CEP55, EGFR, EXO1, FGFR4, and MAPT associated with both types of breast cancer." (PMID 32724790, 2020).
breast carcinoma (continued). "Likewise, quantitative polymerase chain reaction (PCR) analysis showed that the expression of Cyclin D1 mRNA was diminished in SHP2 knockout breast cancer cells, whereas that of Cyclin E1 was unchanged." (PMID 32944401, 2020). "Using the survival analysis, we found that CCNE1, NPBWR1, A2ML1 and TTK might act critical functions in the oncogenesis and progression of BRCA1/2-mutant breast cancer, reflected by their diagnostic efficacy for BRCA1/2 mutations and prognostic value as well." (PMID 31998560, 2020). "FBXW7 mutations and amplification of CCNE1 (the gene that encodes cyclin E1) occur in these tumor types (FBXW7 mutations: approximately 1.5% of breast and ovarian cancers; CCNE1 amplification [> 4 copies]: 2.3% in breast cancer, 17.6% in ovarian cancer based on TCGA_B38 data)." (PMID 32076484, 2020). "Furthermore, targeting cyclin E1 induced cell cycle arrest and apoptosis in breast cancer cells and hepatocellular carcinoma cells." (PMID 31731635, 2019). "Furthermore, significant evidence indicates that breast cancer patients with higher levels of CCNE1 show a higher mortality rate when compared with those bearing low CCNE1 levels." (PMID 24402230, 2014). "Similarly, breast cancer patients with higher levels of cyclin E1 also showed higher mortality compared with low cyclin E1 patients." (PMID 24112607, 2013). "The artificial upregulation of miR-497 using cyclin E1 as a therapeutic agent could offer a promising new direction for future breast cancer treatment." (PMID 24112607, 2013). "Our study validated the existence of activated ERRα-CCNE1 signaling pathway in HER2-positive breast cancer cell line–SK-BR-3, which suggests that the dysexpression of ERRα may be one of the factors contributing to the over-expression of CCNE1 in breast tumor." (PMID 22723937, 2012). "According to the result of genome-wide identification of direct target genes of ERRα in breast cancer cell lines, cell cycle protein cyclinE1 (CCNE1), which regulates the progression of cell cycle from G1 to S phase, could be a direct target gene of ERRα." (PMID 22723937, 2012). "The observation that cancer cells harbouring CCNE1 gene amplification are sensitive to CDK2 inhibitors provides a rationale for the testing of these chemical inhibitors in a subgroup of patients with ER-negative grade III breast cancers." (PMID 22433433, 2012). "Similar to ERBB2 amplification in breast cancer, high-level CCNE1 amplification may therefore have predominant clinical utility in identifying patients most likely to have a poor response to standard treatment." (PMID 21103391, 2010). "Additionally, other miRNAs that have been reported to directly bind to and regulate CCNE1 expression in breast carcinoma, including hsa‐miR‐15a, hsa‐miR‐483‐3p, and hsa‐miR‐30c‐2‐3p, may also contribute to this differential regulation." (PMID 40548926, 2025). "Thus, circ_6014 could influence breast cancer cellular proliferation via regulation of the cell cycle through changes in CDK2/CCNE1 and CDK4/6/CCND1 cell cycle proteins and regulation of the G0/G1 phase of the cell cycle." (PMID 35383130, 2022). "Thus, we confirmed direct binding between miR-874-3p and CCNE1 in breast cancer cells." (PMID 37303942, 2021). "Notably, among those genetic alteration events whose loss enhances CDK4/6i sensitivity, CDK6, CCND3, CCNE1 and E2F3 were frequently amplified in the genomes of breast cancer patients, whereas among the genes whose loss promotes resistance, RB1, REXO2, PPP2R2A and STT3A were mainly depleted." (PMID 34508104, 2021). "Therefore, the LINC02568/miR-874-3p/CCNE1 regulatory network functions in breast cancer." (PMID 37303942, 2021). "Additionally, CCNE1 exerts important regulatory actions in breast cancer progression." (PMID 37303942, 2021). "Thus, LINC02568 aggravated breast cancer malignancy by modulating miR-874-3p/CCNE1." (PMID 37303942, 2021).
breast carcinoma (continued). "Many researches have presented that Cyclin E1 could mediate the progression of many tumors, such as hepatocellular carcinoma, ovarian cancer, and breast cancer." (PMID 33537306, 2020). "Furthermore, by means of targeting Cyclin E1 directly, miR-15a also play a major role in promoting cell apoptosis and mediating cell-cycle arrest of breast cancer, make it clear that miR-15a possesses tumor suppressive activity in a cell line of breast cancer." (PMID 30733644, 2019). "Taken together, these results demonstrate that breast cancer cells harbouring CCNE1 gene amplification are dependent on CDK2 expression and kinase activity for their survival and suggest that CCNE1 amplification may constitute a potential biomarker of sensitivity to CDK2 inhibitors." (PMID 22433433, 2012). "In luminal (ER+) breast carcinoma (BC), miRNA profiling identified miR‐195‐5p as a key regulator of proliferation that targets CHEK1, CDC25A, and CCNE1." (PMID 40548926, 2025). "We also analyzed our own ER+ breast cancer patient cohort (NCT04526587), comparing the expression of CCNE1 and CDKN2A before and following progression on CDK4/6 inhibitor-based treatment." (PMID 39924553, 2025). "Cyclin E1 (CCNE1) and Progesterone Receptor (PGR also known as PR), represent two well known breast cancer genes present in the PAM50 signatures that are used to delineate the different molecular subtypes of breast cancer." (PMID 39003292, 2024). "Previous studies have identified concomitant focal amplification of CCNE1 and ERBB2 in gastric cancer as well as breast cancer." (PMID 38717153, 2024). "CDK2, a critical regulator of the cell cycle, is a promising drug target, especially in cancers with cyclin E1 protein overexpression, including HR+/HER2− breast cancer resistant to CDK4/6 inhibitors." (PMID 39184861, 2024). "Mechanistically, there were confirmed binding sites between hsa_circ_0006014 and miR-885-3p, and hsa_circ_0006014 promoted breast cancer cell proliferation partially by sponging miR-885-3p and influenced CDK2/CCNE1 and CDK4/6/CCND1." (PMID 35383130, 2022). "We found that decreased expression of circ_6014 decreased the protein expression levels of PCNA, CDK2/CCNE1, and CDK4/6/CCND1, and overexpression of circ_6014 increased the expression of these proteins in breast cancer cells (Student’s t test, p < 0.05)." (PMID 35383130, 2022). "In this study of breast cancer, our cell experiments revealed that overexpression of S6K1 increased the protein levels of c-Myc, thus activated the transcription of cyclin E1, which is consistent with findings of previous studies." (PMID 36042494, 2022). "Both CCNE1 and PLK1 were highly expressed and were related to worse survival outcomes in breast cancer, indicating that they are suitable candidate targets for cancer treatment." (PMID 36393842, 2022). "In order to better understand the effect of different cyclins in breast cancer, we analyzed their expression through the TCGA BRCA database and selected CCNE1, which was highly expressed in tumor, as further research object." (PMID 33791304, 2021). "In order to further understand the relationship of SENP3-EIF4A1, miR-195-5p, and CCNE1 expression in TNBC, Pearson correlation analysis was used in clinical breast cancer samples and TCGA BRCA database." (PMID 33791304, 2021). "We found that eight cyclins (CCNA2, CCNB1, CCNB2, CCND2, CCNE1, CCNE2, CCNF, CCNO) were differentially expressed between breast cancer and normal tissue samples, with the cut-off criterion of log2(fold change) >1, p < 0.05." (PMID 33791304, 2021).
breast carcinoma (continued). "We observed a high frequency (>50%) of copy number gain at three well-known breast cancer loci that contain potential oncogenes (chr8p11.23 [ZNF703] n = 8, 53.3%; chr8q24.2 [MYC] n = 9, 60%; chr19q12 [CCNE1] n = 9, 60%)." (PMID 34535742, 2021). "Rescue experiments revealed that increased miR-874-3p or decreased CCNE1 expression recovered cell growth and motility functions induced by LINC02568 in breast cancer cells." (PMID 37303942, 2021). "The proteins, cyclin B1, cyclin E1, 4E-BP1, PKC-α, and RAB 25 were highly correlated with mRNA expression in breast cancer." (PMID 33324562, 2020). "Among them, CCNE1 and KRT20 were of high expression in BRCA1/2-mutant breast cancer, and ALB and MYOM2 were of low expression." (PMID 31998560, 2020). "For breast cancer, HER2-enriched specific amplification of ERBB2, basal-specific amplification of CCNE1, and luminal B specific amplification of CCND1 were remarkably salient in both TCGA and METABRIC data." (PMID 30885118, 2019). "Beyond question, the dysregulation of cyclin E1/CDK2 kinase activity is involved in oncogenesis in ovarian cancer, bladder cancer, and breast cancer, among others." (PMID 30675171, 2019). "Overexpression of the cyclin E1/CDK2 complex also has been reported in immortalized rat embryo fibroblasts and breast cancer cells." (PMID 30634632, 2019). "We observed that transfection with SALL1 significantly increased the gene expressions of Cyclin A2, Cyclin B1, Cyclin E1, CDK2 and CDK4 in breast cancer MDA cells, which are important for checkpoint regulation in G1-S transition and S phases." (PMID 29625565, 2018). "In breast cancer, the binding of HuR to CCNE1’ 3’-UTR significantly increases the mRNA stability and protein half-life of CCNE1, thus promoting breast cancer proliferation." (PMID 29351796, 2018). "CCNE1 amplification has been reported to be the mechanism of resistance in ER-positive and HER2-positive breast cancers as well as high-grade serous ovarian cancer." (PMID 30521023, 2018). "In silico analyses showed that CCNE1/RB1 ratio correlated with palbociclib IC50 in different datasets of both breast and non-breast cancer cell lines, performing better than CCNE1 or RB1 taken separately." (PMID 30511015, 2018). "MYB has been reported to directly activate the expression of CCNE1 (in normal and transformed colonic epithelium and CCNB1 (in leukaemia and breast cancer cells;." (PMID 26812885, 2016). "Many known drivers of breast cancer, including GATA3, CCNE1, CDK4 and GRB7, as well as known drivers for other tumor types were identified among the FBC candidate drivers." (PMID 24194916, 2013). "We identified many known drivers of breast cancer and other types of cancer, in the female dataset (e.g. GATA3, CCNE1, GRB7, CDK4)." (PMID 24194916, 2013). "CCNE1 and CCNE2 expression has been compared in breast cancer, where these studies are representative of the majority of studies on the relationship of CCNE1 to breast cancer." (PMID 20180967, 2010). "In breast cancer cells, gene knockdown has been shown to decrease CCNE1 expression and Cyclin E1/CDK2 activity." (PMID 21103391, 2010). "Both evaluated miRNAs exhibited significant downregulation in breast carcinomas compared to adjacent mammary tissues and, in contrast, the expression of CHEK1, CDC25A and CCNE1 genes was significantly increased in malignant versus adjacent tissues (N = 18, P < 0.01 for all)." (PMID 40548926, 2025). "In breast cancer, the combination of CDK4/6i with endocrine therapy became standard procedure and is certainly essential to restrict adaptive events, via reduction of Cyclin D1 levels and Cyclin E1 activity." (PMID 37964967, 2023). "Besides, seven genes including BRCA1, FN1, CCNE1, CCND1, CHEK1, BUB3, and CDC25A were identified as the hub nodes by the PPI network, and CCNE1 and CHEK1 were confirmed to be related with the prognostic survival of the patients with breast cancer." (PMID 35186236, 2022).